ATAD2 (ATPase family AAA domain containing 2)
Diseases named in the same sentence as ATAD2 in open-access papers (continued):
Sharing a sentence is not in itself a finding about the gene and the disease.
cancer (continued). "ATAD2 has been reported to play an important role in the processes of numerous cancers and validated to be a promising therapeutic target." (PMID 32174193, 2020). "ATAD2 has been reported to play an important role in the processes of numerous cancers and validated to be a potential therapeutic target." (PMID 32174193, 2020). "For example, the BRD proteins BRD9, BRD4, and ATAD2 were focally amplified in multiple cancer types and their increased copy numbers were significantly, positively correlated with higher mRNA expression levels." (PMID 30760718, 2019). "ATAD2 acts as a transcriptional co-regulator of estrogen receptor alpha and AR to promote the expression of genes driving cancer cell proliferation and survival." (PMID 31527644, 2019). "Briefly, ATAD2 is a nuclear coactivator of ER and AR crucial for assembly of chromatin-modifying complexes and proliferation of hormone-responsive cancer cells." (PMID 29301281, 2018). "In this study we describe novel molecular mechanisms that define a new role for ATAD2 in cancer cell proliferation." (PMID 27612420, 2016). "An intriguing fact is the dispensable nature of ATAD2 in cancer cells as well as in exponentially growing ES cells reported here." (PMID 26459632, 2016). "In cancer cells ATAD2 has been proposed to function as a transcriptional co-regulator of several oncogenic transcriptional factors including estrogen receptor (ER), androgen receptor (AR), E2F transcriptional factor and Myc." (PMID 27612420, 2016). "Our study provides a plausible reason for the high expression of ATAD2 in higher grade tumors of diverse origin and thereby suggests a potential new therapeutic target to treat aggressive cancers." (PMID 27612420, 2016). "Early studies of ATAD2 in cancers, considering a series of cancer-related transcription factors, such as Myc, E2F, or androgen and oestrogen receptors, led previous investigators to define ATAD2 as a transcriptional co-activator." (PMID 26459632, 2016). "Taken together, our data show a novel function of ATAD2 in cancer and for the first time identify a reader of newly synthesized histone di-acetylation-marks during replication." (PMID 27612420, 2016). "ATAD2 is co-expressed with genes involved in DNA replication in various cancer types and predominantly expressed in S phase cells where it localized on nascent chromatin (replication sites)." (PMID 27612420, 2016). "We observed that ATAD2 is predominantly expressed in S phase of the cell cycle in primary tumors and cancer cell lines." (PMID 27612420, 2016). "Studies in cancer had shown that ATAD2 is a transcription co-activator acting together with a variety of transcription factors such as E2F, oestrogen and androgen receptors, and Myc." (PMID 26459632, 2016). "Although the conserved AAA ATPase and bromodomain factor, ATAD2, has been described as a transcriptional co-activator upregulated in many cancers, its function remains poorly understood." (PMID 26459632, 2016). "ATAD2 contains both a bromodomain and an ATPase domain and also maps to chromosome 8q24 that is the most commonly amplified region in many types of cancer." (PMID 26697062, 2015). "Combined with the increased efforts to target bromodomain-containing proteins in cancer, ATAD2 seems an attractive cancer protein for more detailed studies." (PMID 26308378, 2015). "In hormone dependent cancer cells ATAD2 is an estrogen and androgen responsive gene and also a co-activator for full activity of ER and AR." (PMID 26308378, 2015). "ATAD2 has been described as an estrogen and androgen responsive gene in hormone dependent cancer cells and a co-activator for full activity of ER and AR, contributing to cancer related proliferation." (PMID 26308378, 2015). "Combined with its apparent wide overexpression in cancers, this leaves ATAD2 as a promising target for therapy in several cancers and calls for further investigations of its expression in specific cancer types." (PMID 26308378, 2015).
cancer (continued). "The mechanism involved in the observed increase in ATAD2 level during cancer development is only partially understood." (PMID 26308378, 2015). "Gene expression alterations in samples with high ATAD2 expression revealed upregulation of several cancer-related genes (B-MYB, CDCs, E2Fs) and gene sets that previously have been linked to aggressive disease and potential for new targeting therapies." (PMID 26308378, 2015). "The gene ATAD2 (ATPase family, AAA domain containing 2; also listed as ANCCA, pro2000) is predominantly expressed in male germ cells, but becomes overexpressed in several cancer forms." (PMID 26308378, 2015). "ATAD2 is detected in the nuclei of cancer cells, with little staining in cytoplasm or surrounding stromal tissue." (PMID 26308378, 2015). "It was demonstrated that ATAD2 is a novel candidate oncogene and possibly a therapeutic target for several types of human cancer." (PMID 24552534, 2014). "Taken together, these data provide evidence that ATAD2 is not only important in HCC cell proliferation but also involved in carcinoma cell migration and invasion." (PMID 24552534, 2014). "High expression of ATAD2 and MYC signaling were also associated with increased risk of cancer progression (p = 0.003 and p = 0.015, respectively), cancer-specific death (p = 0.004 and p = 0.001), and other poor-prognosis features." (PMID 23393560, 2013). "Such a mechanistic association between ATAD2 and MYC, and the finding that MYC-dependent cells are sensitive to ATAD2 knockdown, suggest ATAD2 as a therapeutic target in MYC-dependent cancers." (PMID 23393560, 2013). "ATAD2 maps to chromosome 8q24, a region that is frequently found to be amplified in cancers including in HCC." (PMID 22043308, 2011). "Current ATAD2-targeting approaches, including potential therapeutic strategies such as monoclonal antibodies, RNA-based therapies, and small-molecule inhibitors, provide new opportunities and directions for cancer therapy research." (PMID 41158756, 2026). "Given the evidence linking ATAD2 to paclitaxel resistance across multiple cancers, particular attention should be given to assessing these compounds in paclitaxel-resistant models, with in vivo validation using resistant xenografts to support clinical translation." (PMID 41154392, 2025). "Furthermore, we examine the emerging roles of ATAD2 in mediating resistance to cancer therapies, underscoring its potential as a target for overcoming drug resistance." (PMID 41154392, 2025). "Molecular docking highlighted NM23-H2 and ATAD2 proteins as potential targets, with a higher binding affinity for the former, paving the way for future research on cynthichlorine as a targeted therapy against certain cancers." (PMID 40278293, 2025). "Assessing their effects on resistant cancer phenotypes will provide critical insights into whether ATAD2 inhibition can restore drug sensitivity and advance these compounds toward clinical application." (PMID 41154392, 2025). "By integrating structural insights, mechanistic studies, drug discovery efforts, and the challenges of developing ATAD2-targeted cancer therapies, this review emphasizes the need for further research to optimize ATAD2 inhibition strategies and explore its full therapeutic potential in oncology." (PMID 41154392, 2025). "Higher expression of ATAD2 helps cancer cells to migrate and invade more readily through the EMT." (PMID 41154392, 2025). "Elevated ATAD2 levels are found in many cancers, where it promotes tumor proliferation, survival, and metastasis, and emerging evidence suggests it may contribute to resistance against existing therapies." (PMID 41154392, 2025). "Given the reports of ATAD2 functioning as a co-regulator of these oncogenic transcription factors, we recently analyzed the function of ATAD2 in the cell cycle progression and proliferation of cancer cells and its role in cancer chemoresistance." (PMID 38730681, 2024).
cancer (continued). "Furthermore, ATAD2 is also closely related to the cancer drug response, and deletion of ATAD2 has previously been indicated to induce cancer cell apoptosis, both in drug-sensitive and drug-resistant cancer." (PMID 36632213, 2023). "This strongly supports the role of ATAD2 in regulating cancer de-differentiation status." (PMID 36674511, 2023). "In addition to chromatin remodeling, ATAD2 can also participate in the regulation of DNA replication, DNA damage and repair in cancer." (PMID 36632213, 2023). "Therefore, the regulation of EZH2 expression by ATAD2 plays a significant role in the development of cancer." (PMID 36632213, 2023). "ATAD2 was previously identified as a nuclear co-activator for estrogen (ER) and androgen (AR) receptors regulating the hormone-induced expression of genes involved in the proliferation and survival of cancer cells." (PMID 36674511, 2023). "Moreover, our findings lay a structural foundation for developing cancer therapeutics targeting ATAD2." (PMID 37770645, 2023). "Given the comprehensive cancer-related functions of ATAD2, disrupting the ATAD2-acetyl-lysine interactions has emerged as a potential therapeutic target in cancer, and a lot of pioneering efforts have been made to develop ATAD2 inhibitors from both pharmaceutical and academic settings." (PMID 36632213, 2023). "In short, ATAD2 can indeed promote cancer progression through chromatin remodeling." (PMID 36632213, 2023). "Based on the important roles played by ATAD2 in multiple cancer types, efforts have been focused on developing a new class of potent and specific ATAD2 inhibitors that target its bromodomain, and these inhibitors are currently being tested as therapies for various cancer types." (PMID 37479754, 2023). "In summary, miRNAs could directly target and down-regulate the expression of ATAD2 to control cancer progression." (PMID 36632213, 2023). "Hence, the relevant signal network with ATAD2 as the core plays an important role in various pathways that cancer depends on for survival." (PMID 36632213, 2023). "Interestingly, ATAD2 can regulate the HH pathway to promote cancer development, angiogenesis, invasion, and metastasis." (PMID 36632213, 2023). "Taken together, targeting ATAD2 is a promising strategy for cancer treatment." (PMID 36632213, 2023). "ATAD2 can be targeted to achieve tumor inhibition and therapeutic benefits in some cancers." (PMID 37479754, 2023). "ATAD2 is overexpressed in many different cancer types and plays a role in tumor development." (PMID 37479754, 2023). "Moreover, the dominant structure (AAA + ATPase and bromine domains) can make ATAD2 a potential therapeutic target in cancer, and some relevant small-molecule inhibitors, such as GSK8814 and AZ13824374, have also been discovered." (PMID 36632213, 2023). "Some ATAD2 inhibitors have been discovered over the past few years for cancer treatment." (PMID 37533352, 2023). "Moreover, several studies have established that ATAD2 is overexpressed in many cancer types, including lung adenocarcinoma, breast cancer, colorectal cancer, gastric cancer, hepatocellular tumor, ovarian cancer, and cervical cancer." (PMID 36479043, 2022). "Moreover, we provide evidence suggesting that miR-302 directly targets ATAD2 and thus modulates cancer cell proliferation, migration, and invasion in vitro." (PMID 36139505, 2022). "Next, we determined whether ATAD2 expression is involved in the inhibition of cancer cell migration and invasion by miR-302." (PMID 36139505, 2022). "Our results demonstrate that a high ATAD2 level is significantly associated with a worse outcome in ACC, KIRP, LGG, LUAD, MESO, PAAD TCGA tumors, strongly suggesting that ATAD2 overexpression favors malignant transformation of unrelated cancer types." (PMID 35049055, 2022). "Together, we suggest that ATAD2 might serve as a potential therapeutic target for de‐differentiated solid tumors that strongly exhibit cancer stem cell‐like characteristics." (PMID 35049055, 2022).
cancer (continued). "Moreover, we provide evidence suggesting that miR-302 plays a crucial role in inhibiting cancer cell proliferation, migration, and invasion in vitro and tumor growth in vivo by targeting ATAD2." (PMID 36139505, 2022). "Therefore, ATAD2 is a very promising novel tumor-promoting factor with broad research prospects for the diagnosis and treatment of malignant tumors." (PMID 36008934, 2022). "Altogether, our results clearly demonstrate yet unrecognized association of high ATAD2 expression with cancer stem cell‐like phenotype of solid tumors, regardless of the tumor type." (PMID 35049055, 2022). "However, molecular studies are indispensable in order to determine the exact role for ATAD2 in cancer stem cell‐like phenotype of solid tumors." (PMID 35049055, 2022). "Previously, ATAD2 has been identified as a transcriptional co‐regulator modulating the expression of estrogen and androgen receptors or E2F and c‐Myc transcription factors, all known as cancer/proliferation‐promoting factors." (PMID 35049055, 2022). "ATAD2 is directly associated with estrogen-bound ERα and ACTR, and thus elevates the expression of ERα-targeted cell cycle regulators, such as cyclin D1, Myc, and E2F1, which promote cancer cell proliferation." (PMID 36139505, 2022). "Furthermore, up-regulation of ATAD2 is strongly correlated with poor prognosis in many types of cancer, making the ATAD2 bromodomain an innovative target for cancer therapeutics." (PMID 34502039, 2021). "To test this hypothesis, we set up a parallel study of ATAD2 activity in a series of fundamentally different model systems, namely, S. pombe, human cancer cells and mouse ES cells." (PMID 34580178, 2021). "In this case, it is of great important to know whether ATAD2 is overexpressed in cancer and if, upon its upregulation, ATAD2 alone or interact with other factors could work as a transcription regulator thus promoting malignant transformation and progression." (PMID 33757572, 2021). "The ATAD2 gene has been reported to be overexpressed in a wide variety of cancers, such as endometrial, cervical, ovarian, colorectal, and gastric cancers." (PMID 34298819, 2021). "In addition, ATAD2 is shown to be up-regulated in multiple forms of cancer including breast, lung, gastric, endometrial, renal, and prostate." (PMID 34502039, 2021). "In addition to these roles, ATAD2 is known to be up-regulated in multiple different types of cancer, including breast, lung, gastric, endometrial, renal, prostate, and more recently thyroid." (PMID 34502039, 2021). "Immunohistochemical staining of ATAD2, cancer stem cells (CSCs) markers and immune checkpoint molecules was conducted on human OSCC specimens to determine the expression levels of these proteins and their correlations with the clinicopathological characteristics of ATAD2 in OSCC." (PMID 32669963, 2020). "Thus, it appears that more work is needed before the ATAD2 protein can become a promising target for the treatment of cancers in the future." (PMID 32462022, 2020). "Therefore, it is very urgent to develop new inhibitors targeting ATAD2 that exerts high affinity, selectivity and potent antiproliferatory activity for cancer cells in vitro and vivo." (PMID 32174193, 2020). "ATAD2 overexpression is a poor prognosis marker in various cancers, especially in TNBC21,32,33." (PMID 31527644, 2019). "Recently, androgen regulated BRDs such as BRD2 and ATAD2 increased chromatin accessibility with enhancing AR recruitment to chromatin, which may drive cancer progression." (PMID 31527644, 2019). "Also, the germline-specific chromatin regulator ATAD2 drives various cancer progression phenotypes via transcriptional regulation and is linked to poor prognoses in various cancers and offers an important potential therapeutic target." (PMID 28446200, 2017). "ATAD2, the predicted protein product which contains both a bromodomain and an ATPase domain, maps to chromosome 8q24 in a region that is frequently found amplified in cancer." (PMID 28449718, 2017).
cancer (continued). "Thus, our study provides compelling evidence for a general role of ATAD2 in cancer cell proliferation." (PMID 27612420, 2016). "To test this hypothesis we first asked whether in cancer cell lines ATAD2 expression was also cell cycle-dependent as seen in clinical tumor samples." (PMID 27612420, 2016). "Thus, therapeutic approaches aimed at neutralizing ATAD2 activity are likely to be effective anti-cancer strategies." (PMID 26497681, 2015). "Recent studies suggest that ATAD2 is overexpressed in several cancers and that ATAD2 may have a potential both as a biomarker and as a therapeutic target." (PMID 26308378, 2015). "Several known cancer-testis antigens are expressed, including Atad2, Cep55, and Pbk." (PMID 24621249, 2014). "Furthermore, the functional studies of ATAD2 in this report suggest a potential role of ATAD2 in affecting cell proliferation, invasion, and migration and make ATAD2 an attractive target for future cancer therapeutics." (PMID 24552534, 2014). "Therefore, ATAD2 can be fine-tuning by different regulators to cope with a variety of life processes in cancer, which also provides a theoretical basis for targeting ATAD2 for cancer treatment." (PMID 36632213, 2023). "Thus, in this review, we focus on summarizing the structural features and biological functions of ATAD2 from an epigenetic modulator to a cancer therapeutic target, and further discuss the existing small-molecule inhibitors targeting ATAD2 to improve potential cancer therapy." (PMID 36632213, 2023). "Therefore, ATAD2 serves as a cancer biomarker and therapeutic target." (PMID 37479754, 2023). "More importantly, we systematically summarize the design and discovery of small molecule inhibitors that regulate ATAD2, and the characteristics, advantages and disadvantages of these small molecules, which may provide a cornerstone for the development of ATAD2 target drugs for cancer therapy." (PMID 36632213, 2023). "Thus, lncRNAs also contribute significantly to the regulation of ATAD2 in cancer." (PMID 36632213, 2023). "Undoubtedly, ATAD2 could regulate cancer progression by controlling chromatin remodeling." (PMID 36632213, 2023). "Li et al50 suggested that ATAD2 could regulate cancer stem cell biological features by activating the Hh pathway, as silencing of ATAD2 decreased the proliferation, invasion, migration and colony formation abilities of CSCs which corresponds to the Hh pathway inhibition." (PMID 35049055, 2022). "However, molecular studies are necessary to determine the precise role of ATAD2 in stem cell‐like tumors and to ascertain whether epigenetic functions mediated by ATAD2 are sufficient to promote cancer stemness." (PMID 35049055, 2022). "Also, ATAD2 is co-expressed with genes involved in DNA replication in various cancer types, suggesting that, like Yta7, it might play a role in chromosome replication in multicellular eukaryotes as well." (PMID 35308047, 2022). "The up-regulation of ATAD2 in a variety of diverse cancer types suggests that pharmacological inhibition of its bromodomain function could be beneficial in cancer therapies, and it is currently under investigation by both pharmaceutical companies and research institutes alike." (PMID 34502039, 2021). "Thus, ATAD2 might function as a biomarker for tumor proliferation and metastasis, and as a prognostic factor in many human cancers." (PMID 29515109, 2018). "Indeed, it is possible that in cancer cells, the oncogenic transcription factors use ATAD2 to facilitate their action on chromatin and the resulting malignant transformation would impose a privileged direct or indirect interaction between these factors and ATAD2." (PMID 26459632, 2016).